SEL1L (SEL1L adaptor subunit of SYVN1 ubiquitin ligase)
Description:
Plays a role in the endoplasmic reticulum quality control (ERQC) system also called ER-associated degradation (ERAD) involved in ubiquitin-dependent degradation of misfolded endoplasmic reticulum proteins. Enhances SYVN1 stability. Plays a role in LPL maturation and secretion. Required for normal differentiation of the pancreas epithelium, and for normal exocrine function and survival of pancreatic cells. May play a role in Notch signaling.
Synonyms: IBD2; SEL1L1; Hrd3; NEDGSAF; NEDHGFA; PRO1063; SEL1-LIKE
Tractability: Antibody: UniProt predicts a signal peptide or a membrane-spanning region. PROTAC: ubiquitination databases record sites on it; its protein half-life has been measured.
Gene: Protein-coding gene on chromosome 14 (81,471,547 to 81,533,863, reverse strand). Ensembl gene ENSG00000071537.
Subcellular location: Endoplasmic reticulum membrane
Pathways (Reactome):
Disease: Defective CFTR causes cystic fibrosis; Hh mutants are degraded by ERAD
Signal Transduction: Hedgehog ligand biogenesis; Pre-NOTCH Processing in Golgi
Immune System: AMPK-induced ERAD and lysosome mediated degradation of PD-L1(CD274)
Metabolism of proteins: ER Quality Control Compartment (ERQC)
Transport of small molecules: ABC-family protein mediated transport
Gene Ontology:
Molecular function: protein binding; ubiquitin-like ligase-substrate adaptor activity
Biological process: ERAD pathway; retrograde protein transport, ER to cytosol; protein secretion; protein stabilization; triglyceride metabolic process; protein transport
Cellular component: Derlin-1 retrotranslocation complex; endoplasmic reticulum; endoplasmic reticulum membrane; endoplasmic reticulum quality control compartment; Hrd1p ubiquitin ligase complex; Hrd1p ubiquitin ligase ERAD-L complex; luminal surveillance complex
Genetic constraint (gnomAD): Loss-of-function variants: 40 observed, 96.16 expected, observed/expected ratio (o/e) 0.42, 90% interval 0.32 to 0.54. The upper end of that interval is the gene's LOEUF score, 0.54, which puts it in group 2 of 6, group 1 being the genes least tolerant of losing a copy. Missense variants: 682 observed, 911.98 expected, observed/expected ratio (o/e) 0.75, 90% interval 0.7 to 0.8. Synonymous variants: 349 observed, 328.29 expected, observed/expected ratio (o/e) 1.06, 90% interval 0.97 to 1.16.
Homologues: Orthologues: chimpanzee SEL1L (99% identical), dog SEL1L (98% identical), rabbit SEL1L (97% identical), macaque SEL1L (96% identical), pig SEL1L (96% identical), guinea pig SEL1L (95% identical), rat Sel1l (93% identical), mouse Sel1l (93% identical), tropical clawed frog sel1l (73% identical), zebrafish sel1l (70% identical), Drosophila melanogaster Hrd3 (44% identical), Caenorhabditis elegans sel-1 (37% identical). Paralogues in human: SEL1L2 (41% identical), SEL1L3 (23% identical), DELE1 (10% identical), LRP2BP (10% identical).
Diseases named in the same sentence as SEL1L in open-access papers:
SEL1L is named in the same sentence as 66 diseases in open-access papers, as found by Europe PMC text mining. Sharing a sentence is not in itself a finding about the gene and the disease. The quoted sentences say what the papers report.
Ataxia (7 papers, 2012 to 2025). Ataxia refers to impaired coordination of voluntary muscle movement. "Accordingly, in our study, the dominant phenotypes of Sel1L cKO mice were ataxia and tremor, suggesting that Sel1L inactivation in neurons is a significant cause of cerebellar ataxia." (PMID 39135735, 2024). "This mutation in Sel1L has been linked to the loss of Purkinje neurons and the development of progressive early-onset cerebellar ataxia in dogs." (PMID 39135735, 2024). "Here, we showed that SEL1L deficiency in Purkinje cells leads to early-onset progressive cerebellar ataxia with progressive loss of Purkinje cells with age." (PMID 39352758, 2024). "Further, a homozygous missense mutation in SEL1L gene was reported to be associated with a canine progressive cerebellar ataxia." (PMID 29371607, 2018). "We suggest that the now identified SEL1L mutation (c.1972T>C, p.Ser658Pro) is the most likely underlying cause in FH ataxia." (PMID 22719266, 2012). "SEL1L represents a novel candidate gene for human ataxias and we have initiated mutation screenings in childhood phenotypes." (PMID 22719266, 2012). "We describe here the clinical and histopathological phenotype of a progressive early-onset cerebellar ataxia in FHs and identify a missense mutation in the SEL1L gene that segregates with the recessive disease." (PMID 22719266, 2012). "Additionally, we have identified several patients with SEL1L M528R variant displaying ataxia, while others with SEL1L G585D or HRD1 P398L show mild hypotonia." (PMID 39352758, 2024). "Additionally, recent human studies have found that mutations in Sel1L or Hrd1 are associated with developmental delay and locomotor dysfunction, including ataxia." (PMID 39135735, 2024). "Purkinje cell SEL1L deficiency leads to progressive cerebellar ataxia." (PMID 39352758, 2024). "Overall, our expression data supports the pathogenic role of the SEL1L mutation in FH ataxia." (PMID 22719266, 2012). "Moreover, a SEL1L mutation (p.Ser658Pro) was previously identified in Finnish hounds with cerebellar ataxia (also known as cerebellar ataxia Finnish hound type [CAFH]), further suggesting that SEL1L may play an important role in maintaining normal neurological function or neurodevelopment." (PMID 37943610, 2024). "The clinical phenotypes exhibited by Sel1L cKO mice partially replicate cerebellar ataxia, including progressive tremor, wide stance, hunched back, hindlimb stiffness, progressive hindlimb clasping reflex, and decreased latency to fall in the rotarod test." (PMID 39135735, 2024). "Here we report that SEL1L variant p.Ser658Pro (SEL1LS658P) is a pathogenic hypomorphic mutation, causing partial embryonic lethality, developmental delay, and early-onset cerebellar ataxia in homozygous mice carrying the bi-allelic variant." (PMID 38365914, 2024). "Taken together, these results suggest that Sel1L inactivation in neurons leads to degeneration of Purkinje neurons and results in the clinical phenotypes of cerebellar ataxia in adult Sel1L cKO mice." (PMID 39135735, 2024). "Our recent studies identified several patients carrying the SEL1L or HRD1 variants with hypotonia or ataxia, but the role of SEL1L-HRD1 ERAD in the pathogenesis of cerebellar ataxia remain unknown." (PMID 39352758, 2024). "We confirmed SEL1L expression in the cerebellar cortex, the affected organ in FH ataxia." (PMID 22719266, 2012). "Moreover, the SEL1L S658P variant initially identified in Finnish Hounds with cerebellar ataxia was recently reported to cause early-onset, nonprogressive ataxia in the mouse model expressing the variant." (PMID 39352758, 2024). "Here, we report the identification of 3 biallelic missense variants of SEL1L and HRD1 (or SYVN1) in 6 children from 3 independent families presenting with developmental delay, intellectual disability, microcephaly, facial dysmorphisms, hypotonia, and/or ataxia." (PMID 37943610, 2024). "Mutations in the SEL1L gene have not been previously found in ataxias." (PMID 22719266, 2012).
Ataxia (continued). "In humans, SEL1L ERAD has been reported to be involved in children’s neurodevelopmental disorders, such as developmental delay, intellectual disability, microcephaly, facial dysmorphisms, hypotonia, and/or ataxia." (PMID 41026526, 2025).
glioma (7 papers, 2015 to 2023). A benign or malignant brain and spinal cord tumor that arises from glial cells (astrocytes, oligodendrocytes, ependymal cells). "SEL1L expression is associated with glioma proliferation and severity, as seen in the human brain glioblastoma cells cultured in vitro and in a formalin-fixed paraffin sections of glial tumours." (PMID 33547950, 2021). "In GBM cell lines considered as either glioma initiating stem cells (GISCs) or glioma-associated stem cells (GASCs), the assessment of the expression levels of SEL1L mRNA revealed higher level of transcript in AC compared to NS, regardless of the SNP rs12435998 genotype." (PMID 25948789, 2015). "In the present series of gliomas, SEL1L cellular location was assessed using two overlapping antibodies against the N‐terminal region of the protein that revealed different variants." (PMID 31111685, 2020). "This study aimed to investigate SEL1L expression in 110 adult human gliomas of different molecular subtype and grade using healthy nervous tissue as control." (PMID 31111685, 2020). "We explored the role of SEL1L in 110 adult gliomas, of different molecular subtype and grade, in relation to cell proliferation, stemness, glioma‐associated microglia/macrophages (GAMs), prognostic markers and clinical outcome." (PMID 31111685, 2020). "Our findings in gliomas are based on the immunohistochemical detection of SEL1L with both antibodies." (PMID 31111685, 2020). "All these findings support the involvement of SEL1L, as a member of the ER protein quality‐control machinery, in glioma progression, neo‐angiogenesis affecting TME (both immune cells and ECs), and in modulating efficacy of therapies." (PMID 31111685, 2020). "Because SEL1L is an UPR and ER-associated degradation protein, downregulation of SEL1L sensitizes glioma stem cells to the cytotoxic effects of valproic acid." (PMID 27304053, 2016). "Furthermore, lower expression of Sel1L in glioma stem cells with the SNP rs12435998 genotype was related to enhanced sensitivity to valproic acid." (PMID 29415493, 2018). "In gliomas, SEL1L is down-regulated as well, even though its mechanism is still unclear." (PMID 25948789, 2015). "Surprisingly, knockdown of SEL1L, a crucial protein involved in homeostatic pathways, cancer aggressiveness, and stem cell state maintenance, increased VPA sensitivity to glioma." (PMID 34568018, 2021). "As target genes of three branches, DDIT3 (CHOP) and DNAJB9 (IRE1α-XBP1), but not SEL1L (ATF6) were obviously upregulated in glioma cells after treatment of S4, which declared ATF6 was not the main activated branch." (PMID 37386564, 2023). "SEL1L was not expressed in ECs and vascular pericytes of normal blood vessels or quiescent tumour blood vessels of both LGGs and high‐grade gliomas (HGGs)." (PMID 31111685, 2020). "In the present study, SEL1L overexpression associates significantly with TERT promoter mutation, EGFR gene amplification, LOH on 10q and (borderline) 9p chromosomes, all well‐known negative prognostic markers for gliomas." (PMID 31111685, 2020).
diabetes (5 papers, 2010 to 2026). "Conversely, loss of SEL1L in mouse β cells led to impaired function, loss of β cell identity, and development of diabetes." (PMID 40512624, 2025). "A combined loss of both SEL1L and autophagy in β cells leads to diabetes in mice shortly after weaning, with premature death by approximately 11 weeks of age, associated with marked ER retention of proinsulin and β cell loss." (PMID 36346671, 2023). "The human Sel1l gene is located in a chromosome region that is in close proximity to a type 1 diabetes high risk locus, IDDM-11 (insulin-dependent diabetes mellitus locus 11), prompting the speculation that mutations in Sel1l may be associated with the pathogenesis of type 1 diabetes." (PMID 20170518, 2010). "Further exploration of SEL1L function in the integration of mechanism governing β-cell replication and function may have significant implications for the development of cell-based replacement therapies for diabetes." (PMID 24324549, 2013).
glioblastoma (5 papers, 2011 to 2021). The most malignant astrocytic tumor (WHO grade IV). "A recent study has shown that pTERT mutations are associated with SEL1L overexpression in glioblastoma; high SEL1L immunoreactivity correlates with tumour progression, cell proliferation, decreased OS and poorer response to therapy." (PMID 33547950, 2021). "Further, it was proposed that SEL1L could be an important biomarker in pTERT mutant/EGFR amplified/IDH wild-type subgroup of glioblastoma." (PMID 33547950, 2021). "SEL1L was overexpressed in anaplastic gliomas (World Health Organization [WHO] grade III) and in glioblastoma (GB, WHO grade IV) with the highest labelling index (LI) in the latter." (PMID 31111685, 2020). "Analysis of SEL1L protein profile in the non-tumorigenic human fetal brain cell line CB660 compared to the three glioblastoma cell lines provided further in vitro evidence that p38 was indeed expressed at higher levels in tumor cells." (PMID 21359144, 2011).
Alzheimer disease (4 papers, 2012 to 2021). A progressive, neurodegenerative disease characterized by loss of function and death of nerve cells in several areas of the brain leading to loss of cognitive function such as memory and language. "It must be recalled that SEL1L SNP rs12435998 was previously demonstrated to be an independent susceptibility factor in Alzheimer's disease." (PMID 25948789, 2015). "A tentative association was found between an intronic SEL1L SNP and Alzheimer's disease." (PMID 22719266, 2012). "Polymorphism in SEL1L may also be a susceptibility factor for Alzheimer's disease." (PMID 34220315, 2021).
Obesity (3 papers, 2018 to 2023). Accumulation of substantial excess body fat. "Mice with myocyte-specific SEL1L deficiency exhibit enhanced insulin sensitivity, increased adipose beigeing, and resistance to diet-induced obesity." (PMID 37535424, 2023). "We next investigated how Sel1L deficiency in POMC neurons leads to age-associated obesity, first by measuring food intake and metabolic rates of Sel1LPOMC mice." (PMID 29457782, 2018). "Taken together, these data demonstrate that Sel1L deficiency in POMC neurons leads to age-associated obesity due to overeating, partially due to impaired leptin response at a step downstream of pY-STAT3." (PMID 29457782, 2018). "Mice with POMC neuron–specific Sel1L deficiency developed age-associated obesity due, at least in part, to the ER retention of POMC that led to hyperphagia." (PMID 29457782, 2018). "Loss of SEL1L in myocytes leads to reprogramming of systemic metabolism, including enhanced adipocyte beigeing, increased insulin sensitivity, and resistance to diet-induced obesity, partly through the action of myocyte-derived FGF21." (PMID 37535424, 2023). "To explore the clinical implications of these findings, we investigated the interaction between Sel1L-Hrd1 ERAD and POMC-C28F, a disease-associated mutant identified recently in patients with early onset obesity." (PMID 29457782, 2018). "Here, we report a surprising finding that ERAD involving the Sel1L-Hrd1 protein complex is required for POMC maturation in the ER, which, when defective, upregulates food intake, leading to age-associated obesity as a result of intracellular retention of POMC." (PMID 29457782, 2018). "POMC neuron–specific Sel1L-KO (Sel1Lfl/fl POMC, hereafter referred to as Sel1LPOMC) mice develop hyperphagia and age-associated obesity even on a low-fat diet (LFD), with intracellular retention of POMC." (PMID 29457782, 2018). "In addition, myocyte-specific SEL1L deletion triggered a systemic reprogramming of metabolism characterized by improved glucose sensitivity, enhanced beigeing of adipocytes, and resistance to diet-induced obesity." (PMID 37535424, 2023). "The delay in onset of obesity suggests that impaired Sel1L-Hrd1 ERAD function attenuates, rather than completely blocks, POMC maturation within the ER, and thus, more time is required to develop the obesity phenotype." (PMID 29457782, 2018).
adenoma (2 papers, 2011 to 2017). A neoplasm arising from the epithelium. "However, in the context of colorectal cancer, while basal expression of SEL1L in normal mucosa of the epithelial lining is low, SEL1L is upregulated in adenoma and adenocarcinoma cells." (PMID 29430279, 2017).
agammaglobulinemia (2 papers, 2024 to 2026). A decreased level of serum immunoglobulins. "A biallelic SEL1L C141Y variant causes premature death in 5 patients with early-onset neurodevelopmental disorders and agammaglobulinemia (ENDI-A) due to severe SEL1L-HRD1 ER-associated degradation dysfunction." (PMID 37943617, 2024). "Its most severe form, ENDI with agammaglobulinemia (ENDI-A), results from a bi-allelic SEL1L-Cys141Tyr (C141Y) mutation within its fibronectin II (FNII) domain and currently lacks effective treatment." (PMID 41862645, 2026).
hepatocellular carcinoma (2 papers, 2019 to 2023). A malignant tumor that arises from hepatocytes. "In conclusion, the inhibitory effect of FAM134B on hepatocellular carcinoma (HCC) cell autophagy is attributed to its suppression of endoplasmic reticulum stress‐related degradation factors, including DERL2, EDEM1, SEL1L and HRD1." (PMID 37728036, 2023).
meningioma (2 papers, 2014 to 2015). A generally slow growing tumor attached to the dura mater. "Similarly, a region 5′ to SEL1L was the only duplicated gene significantly associated with meningioma progression in the two SNP cohorts." (PMID 25003081, 2014). "Moreover, SNP association with meningioma stage evidenced that a gene of the ERAD pathway, SEL1L, is likely associated with the malignant transformation of meningiomas, consistent with mQTL, and state-of-the-art knowledge." (PMID 25003081, 2014).
multiple myeloma (2 papers, 2011 to 2021). "We report here two new anchorless endogenous SEL1L variants, p38 and p28, identified in lysates of different cell lines, including KMS11 (multiple myeloma), 293FT (embryonic kidney), MCF7, SKBr3 (breast cancer) and MCF10A (non-tumorigenic breast)." (PMID 21359144, 2011). "We further confirmed that STING could interact with SEL1L and HRD1 in STING-proficient 5TGM1 multiple myeloma cells 28 and that the degradation of the BCR could be blocked by kifunensine (an ERAD inhibitor) or MG132 (a proteasome inhibitor)." (PMID 32999453, 2021).
pancreatic cancer (2 papers, 2023 to 2024). "We identified 12 GRGs differently expressed in pancreatic cancer and selected three genes (SEL1L, TUBA1C, and SDC1) to build a prognostic model." (PMID 38048216, 2023). "A comparison of SEL1L/TUBA1C/SDC1 mRNA expression levels in various pancreatic cancer cell lines using the Cancer Cell Line Encyclopedia (CCLE) database showed that most pancreatic cancer cells expressed less SEL1L than SDC1 or TUBA1C." (PMID 38048216, 2023). "We established a prognostic model based on SDC1/TUBAC/SEL1L with favorable prediction performance for pancreatic cancer." (PMID 38048216, 2023). "High expression of SEL1L in TCGA-pancreatic cancer cohort included 48 upregulated genes and 7 downregulated genes." (PMID 38048216, 2023). "We identified three GRGs closely related to pancreatic cancer: SEL1L, TUBA1C, and SDC1." (PMID 38048216, 2023). "SEL1L expression reduces pancreatic carcinoma cell aggressiveness in vivo and in vitro." (PMID 38048216, 2023). "In one study, downregulation of SEL1L significantly decreased the expression of TIMP and PTEN involving tumor invasion in human pancreatic cancer." (PMID 39176397, 2024). "The SEL1L/TUBA1C/SDC1 mRNA expression levels were compared in normal and pancreatic cancer tissues using TCGA." (PMID 38048216, 2023). "Immune infiltration data from the high- and low-expression SEL1L, TUBA1C, and SDC1 pancreatic cancer groups were gathered using CIBERSORT algorithms." (PMID 38048216, 2023). "Pancreatic cancer samples had a higher expression of TUBA1C and SDC1 compared with the standard samples, while SEL1L expression was lower in vitro and in vivo." (PMID 38048216, 2023). "TCGA-pancreatic cancer data were classified according to NRG expression levels, SEL1L, TUBA1C, and SDC1, and each group was analyzed using GO and KEGG." (PMID 38048216, 2023). "Additionally, we compared the levels of SEL1L/TUBA1C/SDC1 expression in normal and pancreatic cancer tissues using the Human Protein Atlas (HPA) database." (PMID 38048216, 2023).